CRP (C-reactive protein)
Diseases named in the same sentence as CRP in open-access papers (continued):
Sharing a sentence is not in itself a finding about the gene and the disease.
infection (continued). "However, CRP continuously increased in the initial stages of infection for both the patients with severe and those with moderate H1N1." (PMID 21569236, 2011). "CRP is used mainly as a marker of inflammation and infection." (PMID 21430962, 2011). "C-reactive protein (CRP) is a serum marker for inflammation or infection and acts by binding to a chemical (phosphocholine) found on the surface of dead or dying cells (and some types of bacteria) in order to activate the immune system (via the complement system)." (PMID 20877716, 2010). "Currently used conventional infection markers such as the CRP level, the WBC count and the erythrocyte sedimentation rate have relatively poor discriminatory capacity in distinguishing patients with bacterial infections versus patients with nonbacterial infections." (PMID 21034463, 2010). "C-reactive protein (CRP), and erythrocyte sedimentation rate (ESR) are inexpensive, non-invasive tests that are often obtained in subjects with orthopedic implants prior to implant removal to assess for implant-associated infection." (PMID 20179760, 2010). "After an inflammatory stimulus, serum CRP levels may exceed 500 times baseline, so CRP is used in all medical specialities to help diagnose inflammation and infection." (PMID 20877716, 2010). "The statistically significant differences in median CRP levels observed between the three groups of children with different severity of infection were in line with the findings of other studies showing higher CRP levels with higher severity of infection in children." (PMID 20158885, 2010). "Our previous studies indicated that CRP > 6 mg/l and sICAM-1> 300 ng/ml in plasma samples collected in endotoxin free conditions were independent predictors of infection with a high sensitivity for clinical infection (95%) and NPV of 97%." (PMID 20398379, 2010). "The presence of preoperative infection or the use of antibiotics, which might affect the level of CRP or the severity of perioperative systemic inflammation, was not used as an exclusion criterion." (PMID 19861299, 2010). "In summary, PCT may be a more reliable indicator of periprosthetic infection given the substantial proportion of patients with unexplained high CRP levels preoperatively." (PMID 22505973, 2009). "Studies have shown that elevated C-reactive protein concentrations in the postoperative period may predict an increased chance of postoperative infection and anastomotic leakage." (PMID 19319134, 2009). "Both PCT and CRP have limited value in the diagnosis of infection during the administration of ATG." (PMID 19291300, 2009). "Based on the in vitro bactericidal results we hypothesized that CRP and L-ficolin might interact in the patient's serum under infection-inflammation condition with mild acidosis." (PMID 19180241, 2009). "To unequivocally demonstrate that the CRP∶L-ficolin interaction is triggered by infection-inflammation condition, we showed that the L-rFBG interacts avidly with CRP at KD of 1.26×10−8 M under infection-inflammation condition compared to 1.11×10−6 M under normal condition." (PMID 19180241, 2009). "The aim of this study was to evaluate the utility of five markers of infection: C-reactive protein (CRP), procalcitonin (PCT), soluble triggering receptor expressed on myeloid cells-1 (sTREM-1), CD163 and high mobility group box-1 (HMGB1), as markers of SBI in severely ill Malawian children." (PMID 19675669, 2009). "Hence, two typical conditions were defined: (i) the infection-inflammation induced local acidosis (pH 6.5, 2 mM calcium in infected serum with CRP of 10 μg/ml) and (ii) normal condition (pH 7.4, 2.5 mM calcium in normal serum with CRP<0.5 μg/ml)." (PMID 19180241, 2009). "• Both PCT and CRP have limited value in the diagnosis of infection during administration of ATG." (PMID 19291300, 2009). "Indeed, data indicate that vaccination diminishes the infection-induced acute phase response with respect to the CRP- and SAA3-proteins." (PMID 19341445, 2009).
infection (continued). "CRP is better in identifying infection with S. pneumoniae than with E. coli." (PMID 18706087, 2008). "ProET-1 levels had a higher diagnostic accuracy with a high negative predictive value as compared to traditional biomarkers of infection (C-reactive protein and leukocyte count) and in the range of procalcitonin to exclude growth of bacteraemia in blood cultures." (PMID 18304365, 2008). "The established biological markers of inflammation (leucocytes, C-reactive protein) may often be influenced by other parameters than infection, and may be unacceptably slowly released after progression of an infection." (PMID 18620598, 2008). "Therefore, the ability of the C-reactive protein level to return to normal much faster than the erythrocyte sedimentation rate enables it to be a more sensitive indicator of infection, particularly in the early postoperative period." (PMID 18644107, 2008). "CRP is a typical acute-phase reactant and also is a largely studied marker of infection." (PMID 18284667, 2008). "CRP measurement as an indicator of inflammation or infection status is widely used." (PMID 18445267, 2008). "Procalcitonin (PCT) and C reactive protein (CRP) have been used as infection parameters." (PMID 18447945, 2008). "There was no preoperative association between CRP levels and infection: OR = 1.50; 95% CI: 0.27-8.13; p = 0.64." (PMID 17505683, 2007). "By univariate analysis, increasing age, disease severity, polymicrobial infection, intensive care admission, lower haemoglobin, leukocytosis, elevated C-reactive protein, elevated plasma urea, and elevated alanine transferase was associated with in-hospital mortality." (PMID 17877801, 2007). "However, when the data were analyzed using multivariate logistic regression, CRP on the second day and again CRP and IL-6 on the fifth day were the only predictive factors for postoperative infection." (PMID 17505683, 2007). "Taking all this in account, the data suggest that CRP might be the most important predictive factor for postoperative infection." (PMID 17505683, 2007). "IL-6 and CRP increased significantly more in patients with infections." (PMID 17505683, 2007). "IL-6, CRP and LBP appear to be of equal value as diagnostic infection markers in our study." (PMID 16569262, 2006). "A maximum daily CRP variation >4.1 mg/dl was a good marker of infection prediction (sensitivity 92.1%, specificity 71.4%), and in combination with a CRP concentration >8.7 mg/dl the discriminative power increased even further (sensitivity 92.1%, specificity 82.1%)." (PMID 16635270, 2006). "• Daily CRP determinations could be useful as a marker of infection prediction because patients presenting a maximum daily CRP variation >4.1 mg/dl plus a CRP level >8.7 mg/dl had an 88% risk of ICU-acquired infection." (PMID 16635270, 2006). "As a result, the aim of the present study was to evaluate whether serial CRP measurements could be useful as an early predictor of infection." (PMID 16635270, 2006). "In addition, we identified different patterns of CRP progression, with different clinical courses and correlations with infection." (PMID 16635270, 2006). "One subject, who had CRP values > 10 mg· L-1, was excluded from the analysis as CRP values of this order may be indicative of infection or trauma." (PMID 16716211, 2006). "Our results showed that a maximum daily CRP variation >4.1 mg/dl from the previous day's level was highly suggestive of an ICU-acquired infection, and if in addition the absolute CRP concentration reached 8.7 mg/dl, it further increased the predictive value for infection." (PMID 16635270, 2006). "The data of the present study indicate that daily CRP determinations could be useful as a marker of infection prediction, since patients presenting a maximum daily CRP variation >4.1 mg/dl plus a CRP level >8.7 mg/dl had an 88% risk of ICU-acquired infection." (PMID 16635270, 2006). "C-reactive protein (CRP) has been used as a marker of infection for many years." (PMID 16569262, 2006).
infection (continued). "PCT is superior to C-reactive protein in discriminating infections in this setting." (PMID 17038199, 2006). "CRP is used as a parameter to support the diagnosis of infection." (PMID 16956405, 2006). "In the study period, the combination of a maximum daily CRP variation >4.1 mg/dl plus a concentration >8.7 mg/dl further increased the discriminative power for infection diagnosis with a sensitivity of 92.1% and a specificity of 82.1% (positive likelihood ratio 5.2, negative likelihood ratio 0.1)." (PMID 16635270, 2006). "Several studies have shown that CRP could be useful in infection diagnosis as well as in monitoring the response to antibiotic therapy." (PMID 16635270, 2006). "• PCT seems to be superior to CRP in discriminating infection after cardiac surgery." (PMID 17038199, 2006). "Daily CRP monitoring and the recognition of the CRP pattern could be useful in the prediction of ICU-acquired infections." (PMID 16635270, 2006). "The acute phase response e.g. leukocytosis, fever, somnelence, anorexia and acute phase proteins synthesis, such as C reactive protein (CRP) in the liver, is a highly conserved inflammatory response which is rapidly activated by infections or trauma via pattern recognition molecules." (PMID 15904534, 2005). "It is possible that in patients with inoperable non-small-lung cancer, an elevated C-reactive protein concentration might reflect intercurrent infection." (PMID 15150622, 2004). "The rate of increase of CRP (∆CRP; ng/ml/h) may be a more useful parameter to detect infection, since a significant change in ∆CRP was apparent only 12 h after birth." (PMID 18924835, 1998). "However, as expected, CRP levels were significantly higher in the infection group, and discriminant analysis showed that the combination of CRP and SUVr values could statistically distinguish infection from non-infection." (PMID 41594176, 2026). "Absolute PCT concentrations were lower in patients receiving inappropriate empiric therapy (P=0.016), but neither proportional nor absolute changes in PCT or CRP were associated with antimicrobial appropriateness, source control, infecting organism or infection source." (PMID 42113673, 2026). "However, differences begin to emerge after the initial peak period: patients who develop infections or other inflammatory complications often exhibit higher peaks or a failure of CRP to decline in the later postoperative days compared to those without complications." (PMID 41153812, 2025). "Thus, the active infection is likely responsible for the high CRP." (PMID 40407654, 2025). "Among laboratory markers, C‐reactive protein (CRP) serves as an independent predictor for distinguishing LA from ICC and holds the highest diagnostic value among inflammatory indicators, yet its discriminative capacity remains limited for ICC with concurrent infection." (PMID 41356644, 2025). "However, CRP has shown limited diagnostic reliability because of its gradual elevation during the early phases of infection and its frequent elevation in noninfectious conditions." (PMID 40895306, 2025). "In other words, while an early CRP peak is expected from surgical injury alone, an abnormally prolonged or rebound CRP elevation may indicate that the patient’s inflammatory response is being sustained by infection or another pathology." (PMID 41153812, 2025). "Furthermore, all HCWs believed that CRP POCT could help reducing unnecessary antibiotic prescription in childhood infections, and most HCWs felt confident in interpreting the results after the feasibility study." (PMID 41433251, 2025). "Recent research suggests thatthe CRP/albumin ratio may be a novel marker of infection severity." (PMID 40622101, 2025). "Although CRP levels and white blood cell counts were mildly elevated in the early postoperative period, they gradually returned to normal, suggesting that these changes were caused by surgical stress rather than infection." (PMID 40365489, 2025).
infection (continued). "However, this is a common limitation in studies of CRP as an infection marker." (PMID 40319081, 2025). "IL-6 becomes detectable within 1 h after triggering an infectious stimulus, reaches its plateau in 4 to 6 h, and the IL-6 release may be essentially abolished by 36 h, even while the infection remains unchallenged; as IL-6 blood level drops, acute phase reactants (such as CRP) increase." (PMID 40171168, 2025). "Infection management may potentially influence CRP and lymphocyte levels." (PMID 41459073, 2025). "Although CRP is a non-specific marker of inflammation and cannot pinpoint the cause of infection, it could be a useful first-line tool for triaging patients." (PMID 39877415, 2025). "Critics might argue that in both previous studies, the clinical infections were community-acquired, chronic infections that were complicated by concomitant ischemia and pre-existing ulcerations, which might have interfered with the CRP levels." (PMID 40565868, 2025). "However, it’s essential to note that CRP is a non-specific inflammatory marker and its elevation can be associated with other conditions such as infection, trauma, or autoimmune activity." (PMID 41041324, 2025). "Laboratory tests, including complete blood count, erythrocyte sedimentation rate (ESR), C-reactive protein (CRP), and serum alkaline phosphatase—may further assist in differentiating benign lesions from infection or malignancy when imaging findings are inconclusive." (PMID 41462855, 2025). "Moreover, since MDW results can be available even before infection is clinically suspected, it may serve as an early alert marker that complements CRP and PCT." (PMID 41303127, 2025). "Additionally, maternal blood inflammatory markers such as c-reactive protein (CRP) are associated with PTB, and high levels of CRP have been found in patients with the preterm premature rupture of membranes and intra-amniotic inflammation/infection." (PMID 39852229, 2025). "For instance, if CRP remains >100 mg/L on day 4–5 without an obvious cause, we confer with infectious disease specialists and often perform a bronchoscopy or ultrasound as needed to localize infection." (PMID 41153812, 2025). "Importantly, some reports on animal models of bone infection suggested that α1-acid glycoprotein may be a more characteristic serum marker of infection than CRP." (PMID 41346634, 2025). "Previous studies have shown that patients with negative cultures may have lower inflammatory markers, and approximately 50% of infections caused by gram-negative bacteria or fungi can present with normal C-reactive protein (CRP) levels." (PMID 39931362, 2025). "Conversely, infection biomarkers such as procalcitonin and C-reactive protein can help distinguish bacterial infection from immune-mediated inflammation: elevated procalcitonin supports the presence of bacterial infection rather than CRS, whereas CRP may rise in both contexts." (PMID 41186785, 2025). "Notably, several studies have shown that prolonged rupture of membranes (PROM) was associated with higher CRP values in the absence of infection, indicating an inflammatory response associated with PROM." (PMID 41441318, 2025). "The limited association between moderately elevated CRP and proven invasive bacterial infections in the early neonatal period, as well as reports on elevated neonatal CRP in the absence of infection, underlines the difficulties in interpreting CRP in the first days of life." (PMID 41441318, 2025). "However, reliance on static cut-offs (e.g., CRP, hemoglobin, platelet count) may reduce accuracy in patients with borderline values or confounding conditions such as infection or chemotherapy-induced cytopenias." (PMID 41156207, 2025).
infection (continued). "While elevated WBC and CRP at presentation may suggest infection, their role in monitoring response to therapy and informing specific treatment decisions (e.g., timing of discharge, switch from intravenous to oral antibiotics, or decision for re-operation) is less well defined in hand infections." (PMID 41556000, 2025). "Importantly, we did not aim to associate a high postoperative CRP level with various complications such as thrombosis, ischemia, new infections, mortality, or fractures, for which a broader range of literature is available." (PMID 40565868, 2025). "We primarily focused on CRP rise as a marker of infectivity in an attempt to elucidate if the organisms identified were causing systemic infection but not necessarily a blood stream infection." (PMID 41195362, 2025). "First, due the retrospective study design, complete blood counts, C-reactive protein levels, and chest computed tomography scans were not performed after each fever occurrence; thus it is impossible to determine if the fevers were caused by infection." (PMID 40873672, 2025). "Despite this, the median CRP levels remained elevated post-treatment, suggesting that sTREM-1, in conjunction with other biomarkers, could provide a more comprehensive overview of the infection status and the effectiveness of the treatment." (PMID 38611690, 2024). "Moreover, following the infection of mice with certain microbial strains, a reduced level of CRP (C-Reactive Protein) was observed, which strongly indicates that these probiotic strains could mitigate the inflammatory response." (PMID 38891909, 2024). "Dosage of C-reactive protein (CRP), erythrocyte sedimentation rate (ERS) and D-dimer are helpful in diagnosing prosthetic joint infection, but only D-dimer has shown sufficient accuracy in predicting the risk of infection recurrence after a two-stage procedure." (PMID 38761247, 2024). "It was observed that the burn injury with simultaneous infection of P. aeruginosa HW01 caused log-fold increase from the normal level of serum C-reactive protein on Day 2 after burn injury in both treated and untreated animals irrespective of intervention with P. aeruginosa infection." (PMID 38783899, 2024). "Various soluble proteins of the innate immune system such as C-reactive protein (CRP), ferritin, DNase-I and apolipoprotein H (ApoH) could play an important role, both systemically and locally, in the early stages of infection, to contain it, until a specific response is developed." (PMID 39176097, 2024). "Moreover, CRP levels are instrumental in monitoring inflammation and infection." (PMID 39726534, 2024). "Centile reference charts were created based on the “typical” CRP responders to standardise assessment of infection progression and treatment response in patients with suspected BSI; these could be used to guide management independent of microbiological test results." (PMID 38599549, 2024). "However, it can take up to 48 h from the onset of infection before CRP peaks." (PMID 38504318, 2024). "The high CRP values may be due in part to the fact that patients with MRSA infection have a higher proportion of co-viral infections and severe underlying diseases than those with MSSA infection." (PMID 39483528, 2024). "However, a major limitation of CRP as an early indicator of CAL is that elevated CRP levels can result from inflammation rather than signaling an underlying infection or complications such as CAL." (PMID 39483587, 2024). "Some authors even suggest the level of variability of CRP may influence clinical decisions, with one paper studying intensive care unit acquired infections showing daily CRP infection could be used as a marker of infection." (PMID 39485740, 2024). "However, it is important to consider that CRP levels can be influenced by injury or infection." (PMID 38304429, 2024).